TNF (tumor necrosis factor)
Diseases named in the same sentence as TNF in open-access papers (continued):
Sharing a sentence is not in itself a finding about the gene and the disease.
gestational diabetes (continued). "Crocetin decreased the expression levels of IL-6, TNF-α, and IL-1β, increased the levels of antioxidant enzymes such as SOD, GSH-Px, GSH, and CAT, and increased body weight in rats with STZ-induced gestational diabetes mellitus (GDM)." (PMID 38004168, 2023). "Potential involvemehasof hsa-miR-875-5p to regulate TNF, LEP and IRS1 genes in gestational diabetes mellitus was demonstrated in a recent study." (PMID 33670024, 2021). "The purpose of this study was to further evaluate the relationship of various protein markers, including prolactin, HGF, TNFα, TRAIL, PAI-1, RANKL, and OPG, with gestational diabetes in women." (PMID 30147996, 2018). "alterations in the circulating level of tumour necrosis factor-α (TNF-α) has been proposed to be involved in the pathogenesis of gestational diabetes mellitus (GDM), but its role is not completely understood, findings from studies done across different ethnic groups are often inconsistent." (PMID 31448006, 2018). "This study provides novel evidence that gestational diabetes mellitus induces significant neurobiological alterations in the maternal prefrontal cortex, characterized by overexpression of the FBN1 gene, elevated TNF-α levels, and decreased serotonin concentrations in the prefrontal cortex." (PMID 41399726, 2025). "Our study showed that IL-6, TNF-α, and IR had a certain correlation, suggesting that TNF-α and IL-6 could be used as important indicators for the detection and diagnosis of gestational diabetes mellitus." (PMID 32280713, 2020). "This is explained by the fact that when conditioning (controlling), for hair cortisol, gestational diabetes, and pre-gestational diabetes, the relationship between TNF-alpha and gestational weeks is no longer significant." (PMID 31568495, 2019). "This study was therefore designed to compare maternal circulating TNF-α levels between Nigerian pregnant women with and without gestational diabetes mellitus." (PMID 31448006, 2018). "Interestingly it has previously been reported that women with gestational diabetes mellitus show elevated serum levels of CRP, IL-6 and TNF-α." (PMID 25806806, 2015). "A previous study suggested that pEVs from patients with gestational diabetes mellitus (GDM) activate endothelial cells, leading to high level of cytokine secretion, including IL-4, IL-6, IL-8, IFN-γ, TNF-α." (PMID 39996028, 2025). "In addition, AsIV also reduced inflammatory genes IL-6 and TNF-α and suppressed NACHT, LRR, and PYD domain-containing protein 3 (NLRP3) inflammasome-related proteins in the pancreas of gestational diabetes mellitus (GDM) mice, leading to lower blood glucose and insulin levels." (PMID 41011612, 2025). "Similarly, high TNF-α and INF-γ levels were observed in individuals with gestational diabetes." (PMID 37685488, 2023). "EVs isolated from the plasma of women with gestational diabetes induce the release of pro-inflammatory cytokines including granulocyte-macrophage colony-stimulating factor (GM-CSF), interleukin (IL)-4, IL-6, IL-8, interferon-gamma (IFN-γ), and tumor necrosis factor-alpha (TNF-α)." (PMID 36982732, 2023). "When comparing maternal serum TNF-α levels of the study subjects for each level of body mass index, serum TNF-α levels remained significantly higher in both the normal weight and overweight pregnant women with gestational diabetes mellitus compared to their matched controls." (PMID 31448006, 2018). "Adipocytes secrete pro-inflammatory cytokines such as TNF-α, IL-6, and CRP, which interfere with immunological tolerance during pregnancy, promote oxidative stress, and impair endothelial nitric oxide (NO) production—hallmarks of preeclampsia and gestational diabetes mellitus (GDM)." (PMID 40981180, 2025). "Whether polymorphisms in tumor necrosis factor-α (TNF-α), interleukin-6 (IL-6), interleukin-10 (IL-10) or adiponectin (ADIPOQ) influence the risk of gestational diabetes mellitus (GDM) or not remain inconclusive." (PMID 32963590, 2020).
gestational diabetes (continued). "Overall, omega-3 supplementation for 6 weeks in women with gestational diabetes significantly improved gene expression of PPAR-γ, IL-1, and TNF-α; however, it did not affect gene expression of IL-8." (PMID 29385062, 2018). "Adipose tissue-derived cytokines, such as leptin and TNF-α, may impair placental nutrient transport and fetal β-cell development, thereby creating a pro-macrosomic milieu independent of gestational diabetes mellitus (GDM)." (PMID 40655485, 2025).
mucositis (76 papers, 2009 to 2026). Mucositis is inflammation and damage of the mucous membranes lining the mouth and other parts of the gastrointestinal (GI) tract. "Understanding the correlation between TNF-α levels and peri-implant mucositis can provide insights into the mechanisms underlying this condition and inform the development of targeted diagnostic and therapeutic strategies." (PMID 41172495, 2025). "Gut microbiota, reactive oxygen species (ROS), and proinflammatory cytokines such as interleukin-1β (IL-1β), IL-6, and tumor necrosis factor-α (TNF-α) have been implicated in 5-FU-induced mucositis and gastrointestinal toxicity." (PMID 39062024, 2024). "Activation of NF-κB, which is the most studied pathway regarding mucositis development, drives the upregulation of genes that encode for several proinflammatory cytokines, e.g., interleukin-6 (IL-6) and tumor necrosis factor alpha (TNF-α)." (PMID 36451020, 2023). "However, suppressing TNF-α production appears to be well associated with efficacious mucositis modulation." (PMID 37448841, 2023). "Mucositis results in a high inflammatory response via the up-regulation and activation of various transcription factors, ultimately causing elevations in circulating proinflammatory cytokines, in particular IL-1β and TNF-α." (PMID 29872383, 2018). "However, the salivary concentration of IL-6, TNF-α, IL-10, and IL-1β tend to increase because of anticancer treatment especially during the third week, and it seems to be associated with mucositis severity." (PMID 28642709, 2017). "Nevertheless, reduced TNFα and IL-1β expression could alleviate mucositis-associated pain sensation." (PMID 28258409, 2017). "Our results provide important insights into the dynamics of peri-implant mucositis treatment and the role of TNF-α as a potential biomarker." (PMID 41172495, 2025). "Chemotherapy-induced mucositis is exacerbated by increased levels of inflammatory cytokines such as IL-1β and TNF-α, which are important mediators of inflammation." (PMID 40524059, 2025). "Some studies showed significantly higher levels of TNF‐α in the mucositis and peri‐implantitis groups than in healthy groups, while others observed no comparable levels in peri‐implantitis and healthy implants." (PMID 40101934, 2025). "By studying the expression of TNF-α in peri-implant mucositis, we hope to contribute to the growing body of research aimed at improving patient outcomes and ensuring the longevity of dental implants." (PMID 41172495, 2025). "It would also be beneficial to explore the potential synergistic roles of other cytokines and inflammatory mediators alongside TNF-α to identify a more sensitive and specific biomarker panel for peri-implant mucositis." (PMID 41172495, 2025). "IL-1β, TNF-α, and IL-6 were elevated during the third week of therapy, related to the development of worse mucositis in the oral cavity." (PMID 41220465, 2025). "The levels of TNF-α and IL-17 were significantly lower in patients in the treated group compared to peri-implant mucositis before treatment, which corroborates with our study, as treatment progress resulted in a reduction of TNF-α." (PMID 41172495, 2025). "The levels of TNF-α in peri-implant crevicular fluid samples showed a moderate correlation with plaque index, in the Mucositis group." (PMID 41172495, 2025). "Elevated cytokines such as interleukin 1b and tumor necrosis factor (TNF)-α have been found in mucositis related to higher inflammation status." (PMID 39335466, 2024). "For TNF-α, thehypomethylated profile was more frequent in the group of patients who hadrecovered from mucositis." (PMID 38747829, 2024). "Induction of mucositis increased the expression of NF‐κB as well as IL‐β and TNF‐α as evident in immunohistochemical analysis, which is in accordance with the previous knowledge." (PMID 39554361, 2024). "In our immunohistochemical analysis, NF‐κB, IL‐β, and TNF‐α were utilized as markers of tissue injury to assess the impact of FSO on mucositis." (PMID 39554361, 2024).
mucositis (continued). "The hypertrophy/hyperplasia of the oral epithelium together with an increased expression of IL-6 and TNF-α resembles the early events of OM, which have previously been described in a contemporary model of mucositis development." (PMID 36451020, 2023). "For example, promoter SNPs in interleukin-1 beta (IL1B) and tumor necrosis factor alpha (TNF) were related to mucositis after 5-FU treatment in a Japanese population." (PMID 37162533, 2023). "It was observed that the increase in IL-1β and TNF-α levels in Mucositis rats can be reversed by ALA treatment." (PMID 36290656, 2022). "This study showed that proinflammatory cytokines IL-1β and TNF-α are elevated in Mucositis group’s sera and tissues (the stomach, small intestine, or large intestine)." (PMID 36290656, 2022). "The results revealed mucositis-elevated TNF-, IL-1, MDA, MMP-1, -2, -8, and TIMP-1 levels in both tissues and sera, and these values dropped dramatically following ALA treatment." (PMID 36290656, 2022). "Our study also shows that MTX-induced mucositis is accompanied by a significant increase in the pro-inflammatory cytokine TNF-α expression in plasma and remaining small intestinal mucosa." (PMID 33801889, 2021). "Correspondingly, in the present study, we observed increased levels of COX-2, iNOS, IL-8, IL-1β, and TNF-α in mice with CPT11-induced mucositis." (PMID 34795594, 2021). "NF-κB positively regulates the expression of TNF-α and IL-1β, proinflammatory cytokines involved in the amplification of mucositis signals." (PMID 33406583, 2021). "NF-κB activation triggers the activation of multiple signaling pathways for the synthesis of different pro-inflammatory cytokines involved in various stages of mucositis, including TNF, IL-1β, and IL-6." (PMID 31936237, 2020). "In this study, we revealed that DPP-4 inhibitors showed a significant improvement on mice models of 5-FU induced mucositis in diarrhea score, histologic findings, and TNF- α expression." (PMID 31664952, 2019). "Many reports have indicated that patients undergoing chemotherapy would often experience the side effect of mucositis, with the pro-inflammatory cytokines IL-6 and TNF-α playing a key role in chemotherapy-induced mucositis." (PMID 30634582, 2019). "Pro-inflammatory cytokines regulated by NF-κB, such as IL-6, IL-1β and TNF-α, account for an important mechanistic component in the pathogenesis of mucositis." (PMID 28968968, 2017). "In particular, inflammatory mediators, such as tumor necrosis factor- α (TNF-α) and interleukin-1β (IL-1β), were implicated in the complex mechanism underlying the toxic damage to GI epithelium (i.e., mucositis) induced by some CTs, including 5-FU." (PMID 28653974, 2017). "Chang CT noted that the levels of proinflammatory cytokines, such as IL-1β and TNF-α, were elevated in the oral tissue with mucositis developed due to chemotherapy." (PMID 27812611, 2016). "TNF-α is a crucial cytokine involved in the pathogenesis of mucositis, which amplifies the NF-κB signal and initiates mitogen activated protein kinase (MAPK) pathway." (PMID 24367389, 2013). "NFκB is considered a key “driver” of chemotherapy-induced mucositis as its activation correlates with the production of TNF, IL-6 and IL-1β the hallmarks of mucositis inflammation." (PMID 22973511, 2012). "In the past decade, active research has been conducted to define the pathogenesis of mucositis and the role of proinflammatory cytokines TNF-α, IL-6, and IL-1β." (PMID 22973511, 2012). "Signal amplification is the third phase of mucositis development where the inflammation signal is further amplified as a consequence of proinflammatory cytokines such as TNF acting in a positive feedback loop to reinforce NFκB activation." (PMID 22973511, 2012). "The first phase of mucositis during radio-chemotherapy was characterized by the production of inflammatory cytokines, such as IL-1, TNF-α and IL-6, that coordinate this process in the oral mucosa." (PMID 20184737, 2010).
mucositis (continued). "Moreover, MAPKs are directly involved in the transcription and release of TNF-α, a cytokine essential for initiating and sustaining inflammatory cascades in mucositis." (PMID 40244381, 2025). "We hypothesize that elevated TNF-α levels are correlated with peri-implant mucositis, which could suggest a potential biomarker for early detection and management of this condition." (PMID 41172495, 2025). "For example, chemotherapy-induced mucositis, driven by reactive oxygen species (ROS) formation and the production of pro-inflammatory cytokines such as interleukin-1β (IL-1β), IL-6, and tumor necrosis factor-α (TNF-α), leaves mucosal tissue vulnerable to infection and ulceration." (PMID 40149075, 2025). "Stricture in NHL-involved bowel loops may result from mucositis and inflammation, where cytokines like tumor necrosis factor and interleukin-1 contribute to increased intestinal smooth muscle cell proliferation." (PMID 39396490, 2024). "Notably, in another study by our group, we found hypomethylation in the promoter of the pro-inflammatory cytokine TNF-α gene and also in the group recovered from mucositis." (PMID 37372315, 2023). "Its anti-mucositis effect may be through regulating TNF/NF-κB pathway and inhibiting inflammatory mediators PTGS2 and NOS2." (PMID 36278232, 2022). "Previous studies have suggested that TNF/NF-κB pathway and its downstream inflammatory mediators may be effective targets for alleviating chemotherapy-induced mucositis." (PMID 36278232, 2022). "Similarly, radiation‐induced oral mucositis is associated with a significant increase in inflammatory cytokines such as IL1β and TNF‐α and alleviation of mucositis led to a significant decrease in inflammatory cytokines levels." (PMID 35810384, 2022). "Therefore, it is believed that TNF-α, IL-1β and IL-6 are involved in mucositis and have been the targets of inhibition." (PMID 34310611, 2021). "TNF-α, IL-6, IL-1β, and cell apoptosis played a critical role in the development of mucositis." (PMID 33841399, 2021). "In fact, expressions of TNF-α, IL-1β and IL-6 were also found to be increased in response to the 5-FU treatment, indicating that inflammatory cytokines play a key role in the pathogenesis of mucositis induced by chemotherapy and radiotherapy." (PMID 34310611, 2021). "Interestingly, we revealed that DPP-4 inhibitors showed a significant improvement on mice models of 5-FU induced mucositis in diarrhea score, histologic findings, and TNF- α expression." (PMID 31664952, 2019). "In conclusion, the study demonstrated that AzP might regulate the MEK/ERK MAPK signaling pathway to attenuate MCP-1, TNF-α, and IL-6 production and provide opportunities for the development of new anti-inflammatory drugs targeting mucositis." (PMID 30634582, 2019). "The aim of this study was to evaluate the levels of salivary biomarkers IL-1β, IL-10, RANK, OPG, MMP-2, TG-β and TNF-α in individuals with diagnosis of peri-implant mucositis in the absence or presence of periodontal and peri-implant maintenance therapy (TMPP) over 5 years." (PMID 30810638, 2019). "Interestingly, whilst IL-1β and TNF-α are key proinflammatory cytokines instigating sickness behavior responses, they also play a pivotal role in the pathogenesis of mucositis." (PMID 29872383, 2018). "Pentoxifylline’s rationale as a mucositis intervention is based on its anti-TNF activity." (PMID 28642709, 2017). "Regarding mediators that might be altered by ApoE mimetic peptides, TNF-α and IL-1β are important pro-inflammatory cytokines activated by NF-κB pathway, which is up-regulated during the pathogenesis of 5-FU-induced mucositis." (PMID 22524518, 2012). "Its role in potentiating inflammatory and immune responses by inducing various proinflammatory cytokines production such as TNF, IL-6 and IL-1β involved in the development of mucositis has been widely recognised with the use of animal models and in the clinical setting." (PMID 22973511, 2012).